ERBB4 (erb-b2 receptor tyrosine kinase 4)
Description:
Tyrosine-protein kinase that plays an essential role as cell surface receptor for neuregulins and EGF family members and regulates development of the heart, the central nervous system and the mammary gland, gene transcription, cell proliferation, differentiation, migration and apoptosis. Required for normal cardiac muscle differentiation during embryonic development, and for postnatal cardiomyocyte proliferation. Required for normal development of the embryonic central nervous system, especially for normal neural crest cell migration and normal axon guidance. Required for mammary gland differentiation, induction of milk proteins and lactation. Acts as cell-surface receptor for the neuregulins NRG1, NRG2, NRG3 and NRG4 and the EGF family members BTC, EREG and HBEGF. Ligand binding triggers receptor dimerization and autophosphorylation at specific tyrosine residues that then serve as binding sites for scaffold proteins and effectors. Ligand specificity and signaling is modulated by alternative splicing, proteolytic processing, and by the formation of heterodimers with other ERBB family members, thereby creating multiple combinations of intracellular phosphotyrosines that trigger ligand- and context-specific cellular responses. Mediates phosphorylation of SHC1 and activation of the MAP kinases MAPK1/ERK2 and MAPK3/ERK1. Isoform JM-A CYT-1 and isoform JM-B CYT-1 phosphorylate PIK3R1, leading to the activation of phosphatidylinositol 3-kinase and AKT1 and protect cells against apoptosis. Isoform JM-A CYT-1 and isoform JM-B CYT-1 mediate reorganization of the actin cytoskeleton and promote cell migration in response to NRG1. Isoform JM-A CYT-2 and isoform JM-B CYT-2 lack the phosphotyrosine that mediates interaction with PIK3R1, and hence do not phosphorylate PIK3R1, do not protect cells against apoptosis, and do not promote reorganization of the actin cytoskeleton and cell migration. Proteolytic processing of isoform JM-A CYT-1 and isoform JM-A CYT-2 gives rise to the corresponding soluble intracellular domains (4ICD) that translocate to the nucleus, promote nuclear import of STAT5A, activation of STAT5A, mammary epithelium differentiation, cell proliferation and activation of gene expression. The ERBB4 soluble intracellular domains (4ICD) colocalize with STAT5A at the CSN2 promoter to regulate transcription of milk proteins during lactation. The ERBB4 soluble intracellular domains can also translocate to mitochondria and promote apoptosis.
Synonyms: HER4; ALS19; p180erbB4
Tractability: Small molecule: an approved drug acts on it; a structure with a bound ligand is known; a high-quality ligand is known; it has a high-quality binding pocket; it belongs to a druggable protein family. Antibody: UniProt places it where antibodies can reach, with high confidence; its Gene Ontology location is reachable by antibodies, with high confidence; UniProt predicts a signal peptide or a membrane-spanning region. PROTAC: UniProt records ubiquitination sites on it; ubiquitination databases record sites on it; its protein half-life has been measured; a small molecule that binds it is known. Other modalities: a drug acting on it is in phase 1 trials.
Target class: Kinase; Protein Kinase; Tyrosine protein kinase EGFR family; Enzyme; TK protein kinase group
Gene: Protein-coding gene on chromosome 2 (211,375,717 to 212,538,841, reverse strand). Ensembl gene ENSG00000178568.
Subcellular location: Cell membrane; Nucleus (ERBB4 intracellular domain); Mitochondrion
Pathways (Reactome):
Signal Transduction: Downregulation of ERBB2 signaling; Downregulation of ERBB4 signaling; ERBB2 Activates PTK6 Signaling; ERBB2 Regulates Cell Motility; Estrogen-dependent gene expression; GRB2 events in ERBB2 signaling; Nuclear signaling by ERBB4; PI3K events in ERBB2 signaling; PI3K events in ERBB4 signaling; PI5P, PP2A and IER3 Regulate PI3K/AKT Signaling; PIP3 activates AKT signaling; RAF/MAP kinase cascade; SHC1 events in ERBB2 signaling; SHC1 events in ERBB4 signaling; Signaling by ERBB2; Signaling by ERBB4
Disease: Constitutive Signaling by Aberrant PI3K in Cancer; Signaling by ERBB2 KD Mutants; Signaling by ERBB2 TMD/JMD mutants
Neuronal System: Long-term potentiation
Gene Ontology:
Molecular function: epidermal growth factor receptor binding; neuregulin receptor activity; protein binding; protein homodimerization activity; protein tyrosine kinase activity; transcription cis-regulatory region binding; transmembrane receptor protein tyrosine kinase activity; ATP binding; epidermal growth factor receptor activity; GABA receptor binding; protein kinase activity
Biological process: cell migration; cell surface receptor protein tyrosine kinase signaling pathway; ERBB4 signaling pathway; ERBB4-ERBB4 signaling pathway; lactation; mitochondrial fragmentation involved in apoptotic process; negative regulation of cell population proliferation; peptidyl-tyrosine phosphorylation; positive regulation of cell population proliferation; positive regulation of DNA-templated transcription; positive regulation of ERK1 and ERK2 cascade; positive regulation of receptor signaling pathway via JAK-STAT; positive regulation of tyrosine phosphorylation of STAT protein; protein autophosphorylation; signal transduction; cardiac muscle tissue regeneration; central nervous system morphogenesis; embryonic pattern specification; epidermal growth factor receptor signaling pathway; heart development; mammary gland alveolus development; mammary gland epithelial cell differentiation; negative regulation of apoptotic process; nervous system development; neural crest cell migration; and 13 more
Cellular component: basolateral plasma membrane; mitochondrion; nucleus; plasma membrane; receptor complex; basal plasma membrane; cytosol; extracellular region; mitochondrial matrix; nucleoplasm; postsynaptic membrane; GABA-ergic synapse; glutamatergic synapse; membrane; neuromuscular junction; organelle; postsynaptic density membrane; presynaptic membrane
Genetic constraint (gnomAD): Loss-of-function variants: 33 observed, 123.68 expected, observed/expected ratio (o/e) 0.27, 90% interval 0.2 to 0.36. The upper end of that interval is the gene's LOEUF score, 0.36, which puts it in group 1 of 6, group 1 being the genes least tolerant of losing a copy. Missense variants: 1,137 observed, 1,430.1 expected, observed/expected ratio (o/e) 0.8, 90% interval 0.76 to 0.83. Synonymous variants: 504 observed, 509.7 expected, observed/expected ratio (o/e) 0.99, 90% interval 0.92 to 1.06.
Gene-disease validity (ClinGen):
ClinGen rates the evidence that ERBB4 causes each of these diseases.
amyotrophic lateral sclerosis type 19 (autosomal dominant): Limited.
Cancer hallmarks: suppression of growth (promotes); escaping programmed cell death (promotes); escaping programmed cell death (suppresses); proliferative signalling (promotes)
Homologues: Orthologues: macaque ERBB4 (99% identical), rabbit ERBB4 (99% identical), dog ERBB4 (98% identical), pig ERBB4 (98% identical), mouse Erbb4 (97% identical), rat Erbb4 (97% identical), chimpanzee ERBB4 (96% identical), guinea pig ERBB4 (94% identical), tropical clawed frog erbb4 (83% identical), zebrafish ERBB4 (74% identical), zebrafish erbb4a (72% identical), zebrafish erbb4b (53% identical). Paralogues in human: EGFR (48% identical), ERBB3 (46% identical), ERBB2 (44% identical), EPHA3 (16% identical), EPHA2 (15% identical), EPHA4 (15% identical), EPHB2 (15% identical), EPHB1 (15% identical), EPHA5 (15% identical), EPHA7 (15% identical), IGF1R (15% identical), INSR (15% identical), and 41 more.
Diseases named in the same sentence as ERBB4 in open-access papers:
ERBB4 is named in the same sentence as 276 diseases in open-access papers, as found by Europe PMC text mining. Sharing a sentence is not in itself a finding about the gene and the disease. The quoted sentences say what the papers report.
breast carcinoma (223 papers, 2004 to 2025). "EGFR (HER1) and ERBB2 (HER2) are frequently implicated in breast, lung, ovarian, and other malignancies, whereas ERBB3 (HER3) is commonly associated with breast cancer, and ERBB4 (HER4) has been detected in both breast cancer and granulosa cell tumors." (PMID 41230212, 2025). "Male tumors expressed lower levels of Erbb4, a gene implicated in aggressive breast cancer phenotypes." (PMID 39684829, 2024). "This means that higher levels of miR-665 will lead to a higher risk of breast cancer development in persons with the CC ErbB4 rs1836724 SNP genotype." (PMID 37894282, 2023). "Our project aimed to analyze the association between ERBB4 and different breast cancer clinical and molecular subtypes, in order to unveil potential strategies to exploit the modulation of its cellular signaling as a potential anticancer strategy." (PMID 35664762, 2022). "The ability of ErbB4 to translocate into the nucleus and alter transcription has been associated with diverse outcomes, including poor prognostic outcomes in breast cancer." (PMID 36119496, 2022). "We started our project by analyzing the association between ERBB4 expression levels and breast cancer relapse-free patients’ survival (RFS), namely the time that the patient survives without any cancer sign after primary treatment." (PMID 35664762, 2022). "MED1 mediates induction of cell proliferation and migration and the genes associated with it (JUN, FOS, EGFR, VEGF, MMP1, and ERBB4) in breast cancer, which is abrogated when used together with miR-191-inhibition." (PMID 30087366, 2018). "It would be interesting to use the methods stated here to analyze CNV patterns of ERBB4 in other types of cancer with which it has been associated e.g. melanoma, medulloblastoma, and breast cancers." (PMID 29342193, 2018). "Lapatinib has been approved for the treatment of breast cancer patients and a phase II clinical trial of lapatinib for the treatment of stage IV melanoma harboring ERBB4 mutations has recently been concluded (NCT01264081)." (PMID 28060735, 2017). "While ERBB4 was reported to promote differentiation or apoptosis in various studies on breast cancer cells, other studies implicated ERBB4 as a positive regulator of breast cancer growth and potential mediator of trastuzumab resistance." (PMID 26745281, 2016). "Other differentially expressed genes associated with more aggressive breast cancer including ERBB4 and TGFB3 are up-regulated in poor responders in these data." (PMID 27090210, 2016). "In terms of ERBB4, intracellular domain 4ICD of ERBB4 promotes apoptosis of breast cancer cells and cytosolic expression of 4ICD is associated with good prognosis." (PMID 26907936, 2016). "The frequency and prognostic significance of two ERBB4 promoter region variants, -782G/T (rs62626348) and -815A/T (rs62626347), were investigated in a large cohort of breast cancer patients." (PMID 25699077, 2015). "ERBB4 (HER4 receptor tyrosine kinase) methylation has been previously reported in breast carcinomas and significantly associated with worse patient prognosis." (PMID 25366420, 2015). "A genome-wide association study (GWAS) identified a breast cancer risk variant in ERBB4 at 2q34 (rs13393577) to occur in European and Chinese populations." (PMID 25699077, 2015). "Here, we investigated the frequency and prognostic significance of two ERBB4 promoter region variants, −782G>T (rs62626348) and −815A>T (rs62626347), in a cohort of 1010 breast cancer patients." (PMID 25036186, 2014). "Taken together, this study presents a genetic ERBB4 variant as a novel prognostic marker in high-risk early breast cancer and indicates the presence of rare but potentially oncogenic ERBB4 mutations in breast cancer." (PMID 25036186, 2014).
breast carcinoma (continued). "The frequency of nine previously reported somatic ERBB4 kinase domain mutations V721I, A773S, R782Q, G802dup, E810K, P854Q, D861Y, E872K, and T926M, including a mutation previously found in breast cancer (E872K), was also analyzed from the tumor DNA samples." (PMID 25036186, 2014). "Both mutations have been shown to be functional and promote cancer cell/tumor growth in vitro, suggesting the presence of rare but potentially oncogenic ERBB4 mutations in breast cancer." (PMID 25036186, 2014). "We have previously shown that a single nucleotide polymorphism (SNP) −782 G>T in the promoter region of ERBB4 gene is a novel risk variant for breast cancer in German population." (PMID 25036186, 2014). "Here we analyzed the frequencies and prognostic significance of two ERBB4 genetic variants, −782G>T and −815A>T in a cohort of 1010 patients with high-risk early breast cancer." (PMID 25036186, 2014). "ERBB4 mutations are infrequent in breast cancer, with a prevalence of approximately 1%, and ERBB4 gene amplification is rare." (PMID 25516216, 2014). "According to the Catalogue Of Somatic Mutations In Cancer (COSMIC), somatic ERBB4 mutations in breast cancer are rare, as only 1.4% of breast cancers harbor ERBB4 missense mutations (17 out of 1200 patients)." (PMID 25036186, 2014). "Two recent studies have also discovered variants of ERBB4 gene that are associated with increased risk for breast cancer." (PMID 25036186, 2014). "Clinical studies on association of ErbB4 expression with breast cancer patient survival are contradictory, despite in vitro as well as in vivo mouse xenograft data suggesting an oncogenic role for ErbB4 in breast cancer." (PMID 25036186, 2014). "Binding of ERBB4 to its ligands has been linked to oncogenic activity in tumours including breast cancer." (PMID 23681745, 2013). "A subset of cancer tissues demonstrates nuclear ErbB4 immunoreactivty, and nuclear ErbB4 immunoreactivity is associated with poor clinical outcome compared to membranous or cytoplasmic staining pattern in ErbB4-positive breast cancer." (PMID 22761786, 2012). "SNP rs13393577 at chromosome 2q34, located in the Epidermal Growth Factor Receptor 4 (ERBB4) gene, showed a consistent association with breast cancer risk with combined odds ratios (95% CI) of 1.53 (1.37-1.70) (combined P for trend = 8.8 × 10-14)." (PMID 22452962, 2012). "We not only confirmed previously identified loci in Europeans or Chinese populations or both but also found rs13393577 at 2q34/ERBB4 as a new breast cancer susceptibility variant in Korean women." (PMID 22452962, 2012). "It is reported that ERBB4 is frequently overexpressed in breast cancer, and the expression of transcripts encoding the cleavable ERBB4 isoforms was associated with ER expression and a high histological grade of differentiation." (PMID 22452962, 2012). "More recently, the other two members of the ErbB receptor family, ErbB3 and ErbB4, have been implicated in antihormone resistance in breast cancer." (PMID 21396094, 2011). "Nuclear ErbB4/HER4 was also associated with poor prognosis in breast cancer, in contrast to membrane bound ErbB4/HER4." (PMID 17049074, 2006). "Among these concordantly methylated genes, several have known tumor-suppressive activities in PCa, including ERBB4, MCPH1, RBMS3, and AKAP12, High DNA methylation levels of ERBB4 have been associated with poor prognosis and aggressive disease in breast cancer patients." (PMID 40723280, 2025). "For instance, the administration of NRG4 may yield beneficial cardiometabolic effects but simultaneously increase the risk of breast cancer development through prolonged activation of the receptors ErbB3 and ErbB4." (PMID 39872218, 2024). "Interestingly, cytosolic localization of ErbB4 has been associated with better breast cancer prognosis, whilst nuclear localization is associated with worse prognosis." (PMID 36119496, 2022).
breast carcinoma (continued). "For instance, mutations in ERBB4 have been known to be associated with breast cancer." (PMID 35430805, 2022). "In present, most of the reports on ERBB4 gene are associated with breast cancer and schizophrenia." (PMID 29156832, 2017). "The mechanisms linking height to post-menopausal breast cancer risk may go through Ihh signalling as well as ERBB4 signalling and androgen receptor signalling." (PMID 28117334, 2017). "ERBB4/HER4 is the receptor for the Neuregulin family of ligands, with conflicting reported roles in breast cancer that may depend on the splice variant considered." (PMID 28430642, 2017). "Mutations in EGFR, ERBB2, Erb-B2 receptor tyrosine kinase 3 (ERBB3) and Erb-B2 receptor tyrosine kinase 4 (ERBB4) (referred to hereinafter as ERBB family mutations) either occur alone or co-occur with PIK3CA mutations in 19% of HER2-positive breast cancers (n = 58)." (PMID 28750640, 2017). "Interestingly, ERBB4 promotes differentiation in mammary epithelial cells and it is associated with better prognosis in breast cancer patients." (PMID 25879571, 2015). "However, both somatic mutations had previously been shown to be functional and promote cancer cell growth in vitro, suggesting a presence of rare but oncogenic ERBB4 mutations in breast cancer." (PMID 25036186, 2014). "In one breast cancer study, high expression of ERBB4 was associated with a favorable outcome in estrogen receptor-positive cases; in the same study, nuclear ERBB4 immunoreactivity was associated with poor survival as compared with women whose cancer had membranous ERBB4 staining." (PMID 25516216, 2014). "Moreover, we identified rs13393577 in ERBB4 located at 2q34 as a new breast cancer susceptibility variant." (PMID 22452962, 2012). "Rokavec and colleagues identified the presence of five germ-line variants in the ERBB4 5'-untranslated region and reported that one of these variants (ERBB4 -782T > G) was associated with breast cancer risk from the different promoter activity according to the different allele." (PMID 22452962, 2012). "Furthermore, in agreement with the fulvestrant resistance studies, loss of ErbB4 expression has been reported to be an independent marker of tamoxifen resistance in patients with primary breast cancer." (PMID 21396094, 2011). "In breast cancer nuclear localization of ErbB4 receptor has been demonstrated and nuclear ErbB4 expression has been shown to be associated with unfavorable disease prognosis when compared to membraneous ErbB4 expression." (PMID 19171023, 2009). "Interestingly, it has been reported that more nuclearly localized ERBB4 is detected in breast cancer tissue than in normal breast and that nuclear ERBB4 localization associates with worse prognosis than cell surface localization in breast cancer." (PMID 30166589, 2019). "In mammary carcinoma cells, decorin also interacts with ErbB4 and indirectly reduces ErbB2 levels, likely by decreasing ErbB2/ErbB4 heterodimers." (PMID 40136510, 2025). "Previous studies have shown that neuregulin (NRG2) promotes cell proliferation in the subventricular zone via ERBB4 activation, while ERBB4-mediated vasculogenic mimicry has been reported in breast cancer." (PMID 40227858, 2025). "WWP1 also facilitates breast cancer cell tumorigenesis by mediating the degradation of ErbB4, a tumor suppressor in breast cancer." (PMID 40280416, 2025). "Further, it has been shown to function in a growth-promoting autocrine ERBB4/ER signaling feedback loop in human breast cancer cells." (PMID 37855863, 2024). "EGFR, ERBB2, and ERBB4 fusions were most frequently found in glioblastoma, breast cancer and ovarian cancer, respectively." (PMID 37168365, 2023). "We took the three targets with highest predicted probability; ERBB4 (0.790), EGFR (0.784) and ERBB2/HER2 (0.724) all known to be expressed in HER2 + breast cancer, to the causal reasoning analysis stage." (PMID 37715141, 2023).